LGR5 (leucine rich repeat containing G protein-coupled receptor 5)
Diseases named in the same sentence as LGR5 in open-access papers (continued):
Sharing a sentence is not in itself a finding about the gene and the disease.
colon adenoma (13 papers, 2008 to 2022). An adenoma that arises from the colon. "First, APC or CTNNB1 mutations in LGR5+ colon stem cells give rise to human colon adenomas by constitutively activating WNT signaling to sustain the intestinal SC program and bypass cellular differentiation." (PMID 26744320, 2016). "Among the CSCs, the leucine-rich repeat-containing G-protein coupled receptor 5-positive (Lgr5+) stem cells are known to act as the “seed” of colonic adenoma and cancer." (PMID 31947553, 2020). "We next examined the patterns of LGR5 expression in human colon adenomas, carcinomas and distant metastases." (PMID 26744320, 2016). "Median and mean LGR5 gene expression in LGR5+ colon adenomas, carcinomas and liver or lung metastases were 5-10 fold higher than those in normal controls and LGR5− tissues." (PMID 26744320, 2016). "Outgrowth of LGR5+ and LGR5− dysplastic cells beyond the colon crypt structures gave rise to either hybrid LGR5+/LGR5− or LGR5− colon adenomas." (PMID 26744320, 2016). "To identify human colon adenoma-initiating cells, we first performed LGR5 in situ hybridization to examine the spatiotemporal pattern of LGR5+ colon SC during human colon adenoma initiation." (PMID 26744320, 2016). "Overall, these spatiotemporal LGR5 patterns are consistent with a crypt base model of colon adenoma initiation." (PMID 26744320, 2016). "In line with our previous findings, GATA6 has been shown to drive the expression of LGR5 in colon adenoma stem cells." (PMID 26387746, 2015). "In colonic adenomas, Lgr5+ cells were commonly found clustered at the luminal surface and rarely at the crypt base." (PMID 19030762, 2008). "Using standard immunostaining, we compared expression of Lgr5 in normal colon and small intestine vs. small intestinal and colonic adenomas and Barrett's esophagus." (PMID 19030762, 2008). "In addition, many Lgr5+ cells were observed inside the colonic adenoma using fluorescence microscopy)." (PMID 31947553, 2020). "Transformation exclusively occurring in LGR5+ cells could induce growth of colon adenomas." (PMID 24789370, 2014). "In colon cells, LGR5, a WNT signalling component, initiates an intestinal stem cell (ISC) program; however, abnormal LGR5 expression does not initiate premalignant colon adenomas unless other genes, e.g., APC or CTNNB1 (β-catenin), are also mutated to drive aberrant WNT signalling." (PMID 33802849, 2021). "However, in human colon adenoma and carcinoma samples, Lgr5 +stem like cells are highly upregulated and are not confined to the spatial niche as in normal crypts." (PMID 30543324, 2018). "Cross-sections perpendicular to the crypt axes of colon adenomas revealed LGR5+ and LGR5− crypt clustered patterns but not a hybrid LGR5+/LGR5− crypt cluster pattern that may arise from stochastic LGR5 re-expression towards the crypt top." (PMID 26744320, 2016).
Obesity (13 papers, 2008 to 2025). Accumulation of substantial excess body fat. "In the intestine, HFD-induced obesity increases the numbers and function of Lgr5 + intestinal epithelial stem cells in mammals." (PMID 40652248, 2025). "Another proposed mechanism is that diet-induced obesity increases the number and function of Lgr5+ ISCs, while also promoting stemness and tumorigenicity of progenitor cells after inactivation of Apc." (PMID 38590663, 2024). "In mice, obesity mediated by high-fat-diet propagates the population of the colonic Lgr5+ stem cell by stimulating their growth and reducing apoptosis." (PMID 34845203, 2021). "For example, the associations between TCF7L2, TSPAN8/LGR5, FTO and MetS T2D were attenuated when adjusted for BMI, suggesting the role of obesity." (PMID 26599349, 2015). "A very recently published study investigated associations of the type 2 diabetes risk alleles in JAZF1, CDC123/CAMK1D, TSPAN8/LGR5, THADA, ADAMTS9, and NOTCH2 with obesity, insulin sensitivity, and insulin secretion in 4516 Danes." (PMID 18714373, 2008). "Obesity per se has also been shown to induce hypertrophy of the intestinal mucosa, changes to the colonic epigenomic landscape that favor growth, increased ISC proliferation, stemness, and accelerated tumor development in Apc-deficient Lgr5+-ISCs." (PMID 29904634, 2018). "This did not result in an effect of obesity on the mRNA expression levels of LGR5+ (active) ISCs or HOPX (quiescent) ISCs." (PMID 38125020, 2023). "Furthermore, our work reveals a role for the RBP4-STRA6 pathway in regulating HFD-induced expression of LGR5 independent of obesity and, subsequently, the increased kinetics of tumor progression." (PMID 28689994, 2017). "Furthermore, we show that high-fat diet (HFD) increases LGR5 expression and promotes tumor growth in a xenograft model independent of obesity." (PMID 28689994, 2017).
colorectal adenoma (12 papers, 2011 to 2025). An adenoma that arises from the colon or rectum. "Studies investigating the role of LGR5 in early colorectal adenomas found that LGR5-KD reduced the survival of epidermal growth factor (EGF)-treated cancer cells, induced proliferation, and enhanced cell cycle progression." (PMID 39821694, 2025). "Increased LGR5 expression in human sporadic colorectal adenomas and cancers and in murine models have been well described, however, the LGR5 expression profile has not been described in a series of CAC in human." (PMID 33541282, 2021). "Our study shows for the first time that EGF exposure represses LGR5 expression in human colorectal adenoma and tumour cells at both the protein and transcriptional level." (PMID 29149105, 2018). "Regardless of the ‘top-down’ or ‘bottom-up’ theories that have been proposed for CRC initiation, colorectal adenomas are known to harbour LGR5+ cells." (PMID 29149105, 2018). "Epidermal growth factor suppresses expression of LGR5 at both the transcript and protein level in colorectal adenoma and carcinoma cells." (PMID 29149105, 2018). "A recent study, based on the detection of LGR5 mRNA expression by in situ hybridization, provided a more accurate quantitative detection of LGR5 in human colorectal adenomas and adenocarcinomas." (PMID 29652830, 2018). "Our previous work has shown that LGR5 (leucine-rich G-protein coupled receptor 5, Gpr49) serves as a pro-survival factor in early human colorectal adenoma cells." (PMID 29149105, 2018). "LGR5 is overexpressed in human colorectal adenomas and carcinomas relative to normal mucosa: thus LGR5 overexpression is detected from the early stages of colorectal tumourigenesis." (PMID 21829496, 2011). "In this study, we have therefore used different stem-like markers, Msi, CD133, LGR5 and ALDH1 to investigate the presentation of stem-like cells in the different compartment and histological stages of the colorectal adenoma–carcinoma sequence." (PMID 28484082, 2017). "Additionally, in human colorectal adenoma and carcinoma cells, PGE2 treatment up-regulated the protein expression of the Wnt target gene, leucine-rich G-protein coupled receptor 5 (LGR5), which internalizes FZD co-receptor LRP6 and decreases Wnt activity." (PMID 24656144, 2014).
esophageal adenocarcinoma (12 papers, 2008 to 2021). A malignant tumor with glandular differentiation arising predominantly from Barrett mucosa in the lower third of the esophagus. "A mouse model of Barrett’s esophagus (BE), widely considered the precursor lesion to esophageal adenocarcinoma, showed that Lgr5+ gastric cardia stem cells are potentially the cells of origin." (PMID 34885025, 2021). "The analysis of this mouse model of Barrett’s esophagus provided evidence that increasing stem cell marker LGR5 and niche cell marker DCLK1 and decreasing differentiation marker (secretory mucus cells, TFF2+ cells) correlated with a high tumor score." (PMID 28930282, 2017). "Lgr5 was also identified as a marker of poor prognosis in colon, ovary and liver cancers, and was considered to be involved in tumorigenesis in Barrett’s esophagus and esophageal adenocarcinoma." (PMID 24666414, 2014). "Interestingly, with respect to the CSC hypothesis, a Wnt signalling pathway member leucine-rich repeat-containing G-protein coupled receptor 5 (LgR5) showed significance in oesophageal adenocarcinomas (EAC) with and without Barrett’s Oesophagus (BE)." (PMID 30875950, 2019). "Low levels of TFF2 supported the best discrimination between nondysplastic Barrett’s esophagus and Barrett’s esophagus with cancer, followed by high levels of DCLK1, low goblet ratio and high LGR5 expression." (PMID 28930282, 2017).
gastric tumors (12 papers, 2013 to 2025). "LGR5+ gastric tumor cells were able to generate tumors in primary, secondary, and tertiary transplantation, whereas cells from LGR5− tumors lost tumorigenic potential during serial transplantations in vivo." (PMID 39821694, 2025). "In this study, we also observed increased expression of LGR5 in the gastric tumors derived from the H+/K+ ATPase-Cre; LKB1L/L; PTENL/L mice." (PMID 38136437, 2023). "In this study we have outlined an immunosuppressive environment of gastric tumors with high expression of Lgr5, and the complexity of the anti-inflammatory cytokine network associated with it." (PMID 31417548, 2019). "To dissect the mechanism of LGR5-mediated gastric tumor invasion, we examined the effect of LGR5 on cell motility by Phalloidin Staining." (PMID 30089773, 2018). "As documented in the original report, activation of GLI2A in Lgr5+ gastric stem cells led to the rapid development of gastric tumors in the antrum after 3 weeks of doxycycline and vehicle treatment compared to control treated mice." (PMID 30647844, 2018). "In conclusion, our results suggest that LGR5 promotes cellular invasion and migration of gastric tumor cells through Wnt/β-catenin-signaling pathway." (PMID 30089773, 2018). "Activation of GLI2A in Lgr5+ gastric stem cells led to the rapid development of gastric tumors which frequently replaced much of the normal antrum." (PMID 26859571, 2016). "Clearly, further studies are required to unravel the stem cell properties of Lgr5+ cells in gastric tumors." (PMID 24340024, 2013). "In the present study, we investigated the presence of Lgr5+ cells and their biological significance in normal human gastric mucosa and gastric tumors." (PMID 24340024, 2013). "Interestingly, we observed more intense CD133 stained crypts in Apc;Lgr5-EGFP mice with gastric tumors at 5 months compared with weaker signals in control 4 and 9 month-old control mice without tumors." (PMID 35177769, 2022). "Furthermore, we have shown that gastric tumors with higher expression of Lgr5 also exhibit higher levels of TGF-β1 expression." (PMID 31417548, 2019). "The degree and pattern of LGR5 expression varied between the gastric tumors." (PMID 24340024, 2013). "To investigate whether Lgr5+ cells in gastric tumors had any stem cell features, we selected GAs with basally restricted Lgr5+ cells that were reminiscent of the normal crypt and IM, and then divided the tumor glands into upper and lower regions by laser capture microdissection." (PMID 24340024, 2013). "More than half of the tumors exhibited a basal accumulation of Lgr5+ cells, regardless of the histological progression of the gastric tumors, although the overall frequency of LGR5 positivity declined." (PMID 24340024, 2013). "Additionally, to confirm the results from RNA ISH, total RNAs were obtained from FFPE samples of each gastric tumor grade, non-tumorous gastric mucosa, and intestinal mucosa, and the LGR5 transcripts were subsequently measured by semi-quantitative RT-PCR." (PMID 24340024, 2013). "However, it has not been evaluated whether Lgr5+ cells in human gastric tumors retain stem cell properties." (PMID 24340024, 2013).
pancreatic cancer (12 papers, 2013 to 2025). "The possibility of LGR5 being associated with CSCs has also been pointed out in pancreatic cancer." (PMID 35123536, 2022). "Mint3 depletion decreased tumor sphere formation ability and expression of the stemness-related genes SOX2, NANOG, and LGR5 in pancreatic cancer cells." (PMID 32826949, 2020). "According to these findings, it was suggested that the islet’s β-cells expressing LGR5 and Nanog are the initiating cells of pancreatic cancer, which migrated from the islets to form the ductal tissue, after complex mutations and de-differentiation." (PMID 29156578, 2017). "In pancreatic cancer tissue, LGR5 and Nanog staining is observed at the level of the remaining islets and in ductal cancer cells." (PMID 29156578, 2017). "In conclusion, we have demonstrated that LGR5 is expressed in the cytoplasm of pancreatic cancer cells and the basolateral membrane of endocrine cells of the pancreas in patients with PDA." (PMID 24133453, 2013). "We investigated correlations between LGR5 expression in pancreatic cancer cells and survival after surgery." (PMID 24133453, 2013). "LGR5 was also positive in the basolateral membrane of the remaining endocrine cells surrounding the pancreatic cancer tissue." (PMID 24133453, 2013). "Further studies with adequate statistical power and stage-matched cases are needed to verify the prognostic implications of LGR5 in pancreatic cancer, if any." (PMID 24133453, 2013). "Therefore, we report a clinicopathological study of LGR5 expression at the fat invasion front in pancreatic cancer." (PMID 35123536, 2022). "Next, we investigated expression of LGR5 in resected pancreatic cancer tissues." (PMID 24133453, 2013). "Localization of LGR5 in pancreatic cancer cells is consistent with our study." (PMID 24133453, 2013). "Immunoreactivity of LGR5 in endocrine cells was stronger than that in pancreatic cancer cells." (PMID 24133453, 2013). "We hypothesized that LGR5 is a stem cell marker of pancreatic cancer cells on a higher level of the stem cell hierarchy than CD133." (PMID 24133453, 2013). "In 4 of the 9 cases, LGR5 was weakly positive in the cytoplasm of pancreatic cancer cells." (PMID 24133453, 2013). "Although leucine-rich-repeat-containing G-protein-coupled receptor 5 (LGR5), a marker of intestinal stem cells, has been shown to be on a higher level of the stem cell hierarchy than CD133, the expression and function of LGR5 in pancreatic cancer tissue remains unclear." (PMID 24133453, 2013). "The present study therefore, investigated the tissue expression of LGR5 and CD133 in resected pancreatic cancer tissue." (PMID 24133453, 2013). "However, LGR5 expression and its function in pancreatic cancer cells remain unclear." (PMID 24133453, 2013). "LGR5 was strongly positive in the basolateral membrane of a subset of remaining endocrine cells in non-neoplastic tissue surrounding the pancreatic cancer tissue." (PMID 24133453, 2013). "This study investigated tissue expression of LGR5 and CD133 in resected pancreatic cancer tissue." (PMID 24133453, 2013). "Furthermore, compound 11 blocked WNT-3A-induced LGR5 gene expression in human primary hepatocyte spheroids and reduced the viability of RNF43-mutated but not RNF43-wildtype pancreatic cancer cells." (PMID 40992662, 2025). "LGR5 transcript levels in healthy pancreas and pancreatic cancer were not significantly different." (PMID 39169164, 2024). "CSC target genes (CD24, EpCAM, BMI1, and LGR5) were also downregulated after JNKi treatment, suggesting that the JNK pathway might play a role in the regulation of CSCs in pancreatic cancer." (PMID 26840266, 2016). "On the other hand, LGR5 did not co-localize with CD133 in pancreatic cancer tissue." (PMID 24133453, 2013).
pancreatic cancer (continued). "In addition, the expression of three stemness markers of pancreatic cancer including CD133, nestin and Lgr5 was also up-regulated suggesting GEM treatment may stimulate the stem-like properties of cancer cells and enrich a population of cancer stem cells (CSCs) with high drug resistance." (PMID 27531902, 2016).
type 2 diabetes (10 papers, 2008 to 2022). "We identified fourteen type 2 diabetes-associated genes discovered by the first waves of GWAS for which there was little prior evidence of their potential role in diabetes (Adam30, Adamts9, Camk1d, Cdc123, Cdkal1, Cdkn2a, Cdkn2b, Ext2, Hhex, Ide, Jazf1, Lgr5, Thada and Tspan8)." (PMID 23442068, 2013). "Furthermore, a meta-analysis of three GWASs detected six novel variants (in JAZF1, CDC123/CAMK1D, TSPAN8/LGR5, THADA, ADAMTS9, and NOTCH2) that were associated with type 2 diabetes." (PMID 20161779, 2010). "However, it is not unexpected that our study was unable to find significant associations between SNPs in JAZF1, CDC123/CAMK1D, TSPAN8/LGR5 and ADAMTS9 and type 2 diabetes, since the meta-analysis required more than 9000 samples for an 80% power." (PMID 20161779, 2010).
endometrial cancer (9 papers, 2011 to 2025). Primary or metastatic malignant neoplasm involving the endometrium (mucous membrane that lines the endometrial cavity). "We also linked the SOX9+LGR5+ signals to the four molecular subtypes of endometrial cancer defined by TCGA30." (PMID 34857954, 2021). "In addition, the overexpression of LGR5 and SST in endometrial cancer reported with the Oncomine database was also confirmed with GEPIA." (PMID 35163161, 2022). "Moreover, it has also been reported that LGR5, SST, ZNF558, and PTGDS may be involved in the development and progression of endometrial cancer." (PMID 35163161, 2022).
inflammatory bowel disease (9 papers, 2019 to 2025). A spectrum of small and large bowel inflammatory diseases of unknown etiology. "In inflammatory bowel disease, the dysregulation of LGR5 (+) stem cells leads to the disruption of intestinal homeostasis with a deficiency in epithelial crypt structures and tissue regeneration." (PMID 41194856, 2025). "Although it has been known that the self-renewal and differentiation of Lgr5+ stem cells are the foundation to regulate intestinal development, homeostasis, and tissue injury such as inflammatory bowel diseases (IBD), the underlying molecular mechanism is largely unknown." (PMID 39762134, 2025). "The dual role of Wnt/β-catenin is noteworthy: (i) promoting the rapid proliferation of Lgr5+ ISCs by regulating cell cycle progression via cyclin D1, and (ii) exerting anti-apoptotic effects in extra-intestinal tissues —a mechanism that remains underexplored in porcine inflammatory bowel disease." (PMID 41316490, 2025). "Although Lgr5+CBCs play an important role in daily intestinal maintenance, they are highly sensitive to injuries, such as inflammatory bowel disease (IBD) and irradiation." (PMID 32787930, 2020). "Previously, colon organoids expanded from Lgr5+ stem cells were successfully transplanted into the colon epithelium, and organoid transplantation into the gastrointestinal lumen is considered a potential future treatment option for patients with inflammatory bowel disease." (PMID 30842492, 2019). "RNA in situ hybridization (ISH) for LGR5 expression on 30 CACs (12 cases with conventional morphology and 18 cases with non-conventional type morphology) from 29 inflammatory bowel disease (IBD) patients was performed and compared the expression profile to a control group of 10 sporadic CRCs." (PMID 33541282, 2021). "The role of undifferentiated cells, such as leucine-rich repeat-containing G protein-coupled receptor 5 (LGR5)-positive intestinal stem cells, in inflammatory bowel disease (IBD) development, is recognized, particularly within intestinal crypts where DEFA5-expressing Paneth cells are concentrated." (PMID 39329151, 2024).